IL6 (interleukin 6)
Diseases named in the same sentence as IL6 in open-access papers (continued):
Sharing a sentence is not in itself a finding about the gene and the disease.
Obesity (continued). "This latter profile, characterized by a low-grade systemic inflammatory state typical of obesity, is supported by the activation of M1 macrophages, responsible for the production of IL-6, TNF-α and IL-1β and the triggering of Th1 and Th17 cells, as the basis of neutrophilic inflammation." (PMID 40559430, 2025). "In obesity, hypertrophied adipocytes lead to a chronic inflammatory state in adipose tissue, characterized by the infiltration of immune cells and the release of pro-inflammatory mediators, such as IL-6 and TNF-α, contributing to systemic inflammation." (PMID 41020888, 2025). "Furthermore, subgroup analyses indicated a statistically significant reduction in IL-6 levels among studies involving participants with obesity who underwent treatment for durations longer than 12 wk and when synbiotics were used as an intervention." (PMID 41022286, 2025). "Obesity is associated with low-grade inflammation of WAT and infiltration of pro-inflammatory M1 macrophages and increased tumor necrosis factor alpha (TNF-α) and interleukin 6 (IL-6) expression." (PMID 40522819, 2025). "Correspondingly, elevated pro-inflammatory immunological markers such as Interleukin (IL)-1β, Interleukin-6, and Tumor Necrosis Factor-alpha (TNF-α) have been linked to obesity as well as to post-COVID condition (PCC), likely produced by overactivated monocytes and macrophages." (PMID 41323348, 2025). "Obesity has been related to the chronic activation of proinflammatory signaling pathways, in which the NFκB is a critical component that controls the transcription and release of downstream pro‐inflammatory cytokines, such as IL‐6, TNF‐α, and IL‐1β." (PMID 39968210, 2025). "This circuit acts as a potent upstream activator of mTORC1 signaling in obesity-associated HCC, and is cooperatively induced by obesity-driven pro-inflammatory signals (the IL-6/STAT3 axis) and androgen receptor (AR) signaling—providing a molecular explanation for the male predominance in MASH-HCC." (PMID 41208895, 2025). "Indeed, in individuals with obesity and T2D, chronic low-grade inflammation, characterized by elevated IL-6 levels in various tissues, can contribute to reduced insulin sensitivity and impaired glucose metabolism." (PMID 41277875, 2025). "The study suggests that yoga could positively influence cellular biomarkers such as nerve growth factor (NGF), TNF-α, and interleukin-6 (IL-6), which are involved in the progression of oral cancer, obesity, and neurodegenerative disorders." (PMID 40282445, 2025). "In other studies, while no formal mediation analysis was conducted, the association between IMF and cognitive function were robust to adjustment for cardiometabolic conditions, including hypertension, diabetes, obesity, measures of inflammation (leptin, adiponectin, IL-6)." (PMID 39974123, 2025). "While otherinflammatory markers, such as IL-6 and chemokines, are also important, CRP andNLR were chosen for this study due to their greater clinical accessibility,cost-effectiveness, and well-documented associations with both obesity anddepression." (PMID 40926826, 2025). "Furthermore, emerging evidence indicates that gut bacteria-derived metabolites upregulate the production of pro-obesity adipokines, such as leptin, resistin, IL-6, MCP-1, and PAI-1, and downregulate the anti-obesity ones, such as adiponectin." (PMID 40699823, 2025). "Background/Objectives: Obesity is associated with chronic systemic inflammation and elevated levels of inflammatory cytokines such as tumor necrosis factor alpha (TNF-alpha), interleukin-6 (IL-6), and C-reactive protein (CRP)." (PMID 40218888, 2025). "Adipose Tissue and Metabolic Effects: SGLT2is mitigate obesity-associated adiposopathy by shifting macrophage polarization (M1 to M2), reducing proinflammatory cytokines (TNF-α, IL-6), and enhancing adipose tissue browning (UCP1 upregulation) and mitochondrial biogenesis (via PGC-1α/PPARα)." (PMID 40863154, 2025).
Obesity (continued). "Additionally, chronic inflammation associated with obesity triggers NOX activation by releasing pro-inflammatory cytokines (e.g., TNF-α, IL-6), which stimulate redox-sensitive signalling pathways." (PMID 40722947, 2025). "In obesity, particularly with increased visceral fat, adipocytes secrete higher levels of pro-inflammatory cytokines such as interleukin-6 (IL-6) and tumor necrosis factor-alpha (TNF-α), while reducing the secretion of the anti-inflammatory adipokine adiponectin, thereby promoting inflammation." (PMID 41426805, 2025). "Moreover, chemerin levels in newly diagnosed hypertensive patients were significantly higher than in normotensive controls and positively correlated with inflammatory markers (hs-CRP, TNF-α, and IL-6), obesity parameters, plasma TGs, and HOMA-IR index." (PMID 40564199, 2025). "Moreover, IL-6 is involved in regulating insulin action, and elevated levels of IL-6 in obesity are a predictive factor for developing type 2 diabetes." (PMID 40458085, 2025). "Obesity also creates a state of chronic low-grade inflammation-excess adipose tissue secretes pro-inflammatory cytokines (e.g., IL-6, TNF-α) and alters adipokine profiles (leptin up, adiponectin down), fostering a microenvironment conducive to neoplastic growth." (PMID 41041441, 2025). "Overall, these findings suggest that moderating obesity-driven inflammatory pathways, particularly IL-6 signaling and NLRP3 inflammasome activation, may reduce clonal expansion and mitigate the metabolic sequelae associated with CHIP." (PMID 41516113, 2025). "Several observations also suggest that IL-6 may play a key role in asthma pathogenesis, particularly in patients with obesity." (PMID 39714726, 2025). "Elevated IL-6 expression was associated with older age and obesity-related parameters, while RBP4 overexpression correlated with tumor size, lymph node metastasis, advanced TNM stage, and markers of obesity, such as increased BMI and waist circumference." (PMID 41007818, 2025). "Hence, obesity alone and type 2 diabetes with obesity were significantly associated with TNF-α, IL-6, leptin, adiponectin, resistin, and ALR even after adjusting for sex (Model 2) or age (Model 3)." (PMID 40095937, 2025). "In addition, mice overexpressing human IL-6 were protected from HFD-induced obesity, IR and systemic inflammation." (PMID 40794228, 2025). "One argument is that other adipokines (such as IL-6, TNF-α and leptin) predominate in the inflammatory profile in higher obesity states, and resistin, which is more closely linked to immune cell activation, may not scale up further with additional adiposity." (PMID 41011232, 2025). "Independent predictors of AKI include age, race, gender, obesity, diabetes, hypertension, cardiovascular disease, low baseline estimated glomerular filtration rate (eGFR), higher interleukin-6 (IL-6) levels, or requirement of mechanical ventilation and vasoactive drugs." (PMID 39792860, 2025). "Evidence synthesis across multiple RCTs shows that semaglutide reduces hsCRP by 12–20%, TNF-α by 15–40%, and IL-6 by 10–25%, independent of weight loss or glycemic effects, in patients with type 2 diabetes and obesity." (PMID 41511355, 2025). "Elevated IL-6 levels in obesity and central IL-6 resistance must be taken in account." (PMID 40565595, 2025). "Interestingly, obesity itself is also linked to raised pro-inflammatory biomarkers such as TNF-ɑ and IL-6." (PMID 40944249, 2025). "Similarly, tumor necrosis factor (TNF)-α and IL-6 are elevated in the colonic mucosa of individuals with obesity, activating procarcinogenic pathways like NF-κB and ERK 1/2, which promote cell proliferation and survival." (PMID 40722646, 2025). "First, obesity is associated with a state of chronic low-grade systemic inflammation, characterized by elevated levels of pro-inflammatory cytokines, including tumor necrosis factor-alpha (TNF-α), interleukin-6 (IL-6), C-reactive protein (CRP), and resistin." (PMID 40426647, 2025).
Obesity (continued). "The visceral adipose tissue is the main contributor to systemic inflammation in obesity, as it can produce and secrete a greater quantity of pro-inflammatory cytokines, such as leptin, adiponectin, interleukin 6, and tumor necrosis factor-α, which is compared to subcutaneous fat." (PMID 40655405, 2025). "Moreover, IL-6 has been shown to drive macrophages toward an unconventional, pro-inflammatory M2-like phenotype, as seen in aging and obesity, where IL-6-rich macrophages contribute to vascular dysfunction and chronic inflammation." (PMID 40429986, 2025). "Similarly, increased IL-6 in obesity contributes considerably to insulin resistance by activating the JAK-STAT signaling pathway." (PMID 40282189, 2025). "Hepcidin is the main regulator of iron metabolism, and it is upregulated by proinflammatory cytokines such as IL-6, which have shown to be high in conditions like obesity and MetS, leading to reduced iron absorption and availability, which leads to iron deficiency in these individuals." (PMID 40332421, 2025). "Previous studies found that elevated levels of leptin, hs-CRP, IL-6, and reduced levels of adiponectin are linked to obesity, but not necessarily diabetes." (PMID 39940942, 2025). "However, IL-6 levels were significantly higher in obese children (P = 0.001), indicating a link between obesity and inflammation." (PMID 40641901, 2025). "Among them, TNF‐α and IL‐6 serve dual roles as both inflammatory markers and adipokines, contributing to the complex relationship between inflammation, metabolic dysfunction, and obesity." (PMID 40551726, 2025). "Furthermore, obesity is linked to elevated levels of inflammatory mediators, including C-reactive protein (CRP), tumor necrosis factor-α (TNF-α), and interleukin-6 (IL-6)." (PMID 41163684, 2025). "Additionally, obesity induces an increased expression of inflammatory cytokines, such as IL-6 and TNF-α, to promote insulin resistance and metabolic dysfunction." (PMID 40863244, 2025). "However, IL-6 treatment can still improve GSIS in islets from people with obesity and obese type 2 diabetic mice." (PMID 40210633, 2025). "The present study showed that children with comorbid asthma and obesity/overweight had higher IL-6, TNF-α, and leptin, and lower 25-(OH) D3, IL-10, and IL-13 than children with asthma alone, and had lower IL-10 and higher IL-6, IL-13, and leptin than children with obesity/overweight alone." (PMID 40083433, 2025). "GLP-1 receptor agonists, such as liraglutide, semaglutide, and exenatide, have been shown to decrease systemic inflammation by reducing circulating levels of inflammatory biomarkers, including hsCRP, TNF-α, and IL-6, in people with type 2 diabetes, obesity, and cardiovascular disease." (PMID 41511355, 2025). "One possible explanation is that the adipose tissue itself leads to a systemic pro-inflammatory state by promoting the secretion and release of pro-inflammatory mediators such as IL-6, IL-1β, TNF-α, leptin, and MCP-1, so that obesity per se is a risk factor for the development of EDy." (PMID 40005022, 2025). "IL-6 has a complicated and often contradictory role based on its cell or tissue of origin, concentration, and signaling pathways spanning from pro- to anti-inflammatory roles especially with regard to obesity and inflammation." (PMID 40094000, 2025). "Furthermore, obesity has been implicated as a factor in liver diseases and HCC which correlates with our findings of higher secretion of IL-6, IL-2, and MCP-1 in PLWH who are obese." (PMID 41219858, 2025). "In cases of obesity, IL-6 expression significantly increased, displaying dark brownish-yellow cytoplasmic staining, while IL-17 positivity rose, particularly in areas of interstitial inflammation, indicating progressive inflammation and expanded mediator production." (PMID 41133844, 2025). "Repression of IL-6R and IL-6 could be considered as a promising therapeutic approach for the management of obesity." (PMID 40519917, 2025).
Obesity (continued). "The induction of obesity (group 2) led to a significant increase in all monitored inflammatory interleukins compared to the control group (group 1), as observed for IL-1β, IL-6, IL-8, TNF-α, and C-reactive protein, with p < 0.0001 in all cases." (PMID 40565191, 2025). "The relationship between obesity and insulin resistance is driven by adipose tissue inflammation, which stimulates cytokine and chemokine release [including interleukin 6 (IL-6), tumor necrosis factor-alpha (TNF-α), and chemokine (C-C motif) ligand 2 (CCL2)] and macrophage recruitment." (PMID 39928502, 2025). "Obesity-related chronic inflammation might promote tumor by releasing pro-inflammatory factors, such as IL-6 with anti-apoptotic and cell proliferation effect via JAK2 and PI3K/AKT, as well as TNF-α with anti-apoptotic effect via NF-kB." (PMID 40933888, 2025). "On the other hand, obesity selectively increases IL-6 production, predominantly from visceral fat." (PMID 39791741, 2025). "The absence of inflammatory biomarkers (e.g., CRP, IL-6) limits our ability to investigate the underlying mechanisms linking obesity to RA." (PMID 40362866, 2025). "Obesity reduces the level of IL-10 (an anti-inflammatory cytokine), and this, along with overproduction of inflammatory mediators such as tumor necrosis factor-α and IL-6, leads to progression of MASLD." (PMID 40881517, 2025). "In addition, both CRP and IL-6 are affected by metabolic conditions (e.g., obesity and insulin resistance), which can independently affect NO metabolism." (PMID 39981124, 2025). "In another mechanistic study, the obesity-related adipose tissue secretes hormones and inflammatory substances such TNF-α and interleukin-6 (IL-6), which can raise the risk of osteoporosis by accelerating bone resorption and preventing the production of new bone." (PMID 40177287, 2025). "In obesity, where leptin levels are elevated due to increased fat mass and leptin resistance, there is a concomitant increase in IL-6 levels, further contributing to low-grade chronic inflammation that characterizes obesity-related diseases like insulin resistance and cardiovascular disease." (PMID 40218903, 2025). "Elevated IL-6 correlates with asthma severity, particularly in individuals with obesity." (PMID 39714726, 2025). "Obesity is a state of chronic low-grade inflammation, with adipose tissue acting as an active endocrine organ that produces proinflammatory cytokines such as TNF-α, IL-6, and leptin—all implicated in the pathophysiology of psoriasis." (PMID 41010661, 2025). "This may be due to the pro-inflammatory nature of obesity, with over-expression of IL-6, TNF-alpha, and adipokines in visceral and mesenteric fat." (PMID 40156753, 2025). "Obesity represents a major inflammatory source via fat tissue production of IL-6 and TNF-α." (PMID 41425557, 2025). "Overall, bariatric surgery seems to improve the cytokine profile by lowering chronically elevated cytokine levels, such as interleukin-6 (IL-6), but to our knowledge only one study has comprehensively investigated the cytokine profile of 76 markers in obesity and the effects of bariatric surgery." (PMID 40423925, 2025). "The modulation of the tumor microenvironment by obesity-associated molecules, including hormones and pro-inflammatory cytokines (e.g. TNF-α, IL-6) can play a key role in promoting tumor development and progression and, at the same time, in enhancing T-cells function and immune responses to ICIs." (PMID 41278286, 2025). "Moreover, pro-inflammatory cytokines can contribute to skeletal muscle disorders, such as sarcopenia, presenting similar elevated inflammatory markers as obesity, like interleukin-1β (IL-1β), IL-6 and tumor necrosis factor alpha (TNF-α)." (PMID 41141350, 2025). "The association between increased IL-6 and Hs-CRP levels and obesity in this study supports the hypothesis that inflammation plays a significant role in obesity-related metabolic dysfunctions." (PMID 40641901, 2025).
Obesity (continued). "This is notably exacerbated in individuals with obesity, where excess adipose tissue acts as a potent source of pro-inflammatory cytokines such as IL-6, TNF-α, and leptin, which have been shown to enhance tumor cell proliferation, migration, and immune evasion." (PMID 41139205, 2025). "Consequently, obesity raised levels of TNF-α in the circulatory system, which raised the risk of breast cancer associated with insulin resistance and IL-6 production." (PMID 40584290, 2025). "Additionally, the magnitude of postprandial TG and IL-6 responses is more pronounced in individuals with obesity, particularly following larger caloric loads, promoting systemic inflammation and cardiovascular complications." (PMID 41301434, 2025). "Similarly, obesity was linked with higher TNF-α and oxidative stress markers, adipocytokines and increased IL-6, IL-8 and IL-10 in some studies." (PMID 40076848, 2025). "Concurrently, individuals with obesity exhibit elevated levels of pro-inflammatory cytokines, including IL-6, as well as adipokines with pro-inflammatory activity, such as resistin, which contribute to IR and sustain a chronic inflammatory milieu that predisposes to chronic disease." (PMID 41516113, 2025). "Obesity showed a consistent positive association with elevated IL-6, regardless of the presence or absence of asthma." (PMID 39714726, 2025). "CRP is an acute inflammatory protein synthesized in hepatocytes under the primary stimulus of IL-6, reflecting systemic inflammation, which is a component of the state of obesity, T2DM, and atherosclerosis, likely due to cytokine stimulation by adipose tissue, among others." (PMID 40244195, 2025). "In the context of CRC, our findings suggest that obesity-related upregulation of IL-6 may contribute to the creation of a tumor-promoting microenvironment." (PMID 41007818, 2025). "This study assessed the anti-inflammatory potential of a Mediterranean-style ketogenic diet and its effects after 7 months of adherence on systemic inflammation markers (CRP and IL-6) in women with lipedema (n = 24) and a control group with overweight/obesity (n = 24)." (PMID 41010539, 2025). "Pro-inflammatory cytokines, including Interleukin 1 Beta (Il1b) and Interleukin 6 (Il6), are commonly found in WAT and are characteristic indicators of senescence.These cytokines are often associated with the development of insulin resistance in obesity." (PMID 40822955, 2025). "The mechanisms by which Zn contributes to obesity may involve the modulation of leptin and interleukin-6 (IL-6) expression in visceral adipose tissue." (PMID 41459237, 2025). "Chronic inflammation from obesity causes the liver to release inflammatory factors like TNF-α, IL-1, and IL-6, which upregulate hepatic hepcidin synthesis and may reduce erythropoietin synthesis and activity." (PMID 40709336, 2025). "Regarding the effect of inflammation on telomere length values in obesity, the increase in BMI seems to trigger the increased secretion of inflammatory mediators, including fibrinogen, C-reactive protein (CRP), IL-6, and TNF-α, which in turn cause accelerated telomere shortening." (PMID 40566527, 2025). "Since obesity is characterized by a chronic inflammatory response, it has been demonstrated that low Nrg4 levels were negatively associated with inflammatory markers, such as hs-CRP, TNF-α, IL-6, and MCP-1 in conditions of MetS." (PMID 39162358, 2024). "In the whole‐genome association study, one‐third of the differentially methylated genes related to CHD are associated with obesity, among which estrogen receptor 1 ATP binding cassette subfamily G member 1 (ABCG1), and IL6 have been identified as candidate genes for CHD in multiple studies." (PMID 38405061, 2024). "Increased TLR expression in mice with T1DM without associated obesity was accompanied by increased NF-κB, IL-6, IL-12, and TNF-α levels and decreased anti-inflammatory cytokine IL-10 levels." (PMID 39408723, 2024).